KDM4B (lysine demethylase 4B)
Diseases named in the same sentence as KDM4B in open-access papers (continued):
Sharing a sentence is not in itself a finding about the gene and the disease.
gastric cancer (continued). "Previous studies have shown that KDM4B may promote growth in bladder cancer, lung cancer, and gastric cancer." (PMID 27506941, 2016). "In addition, KDM4B mediates gastric cancer cells proliferation under hypoxia by stimulating cyclin A1 gene expression." (PMID 24858415, 2014). "The miR-491-5p acts as an inhibitor of KDM4B in clinical gastric cancer, and it can bind to the 3′UTR of KDM4B mRNA, inhibit the expression of KDM4B and play an anticancer role." (PMID 35186950, 2021). "The radiation-mediated reduction in KDM4B inhibited CCNA1 expression under hypoxia condition, which severely impeded gastric cancer cell proliferation." (PMID 35186950, 2021). "We show that the infection of KDM4B-knockdown cells led to the reduced production of IL-8 as well as CXCL1 and CCL5, which are chemokines involved in gastric cancer progression." (PMID 30683841, 2019). "Hypoxia upregulates KDM4B expression, which demethylates H3K9 at Cyclin A1 promoter, stimulating gastric cancer cell proliferation." (PMID 24858415, 2014). "KDM4B and β-catenin both bind to the promoter of the target gene vimentin, and induce local demethylation of H3K9 markers to increase transcription, thereby promoting gastric cancer metastasis." (PMID 35186950, 2021). "By targeting JMJD2B (KDM4B), miRNA-491-5p can inhibit malignant biological behaviors in GC cell lines, exhibiting the potential as a gastric cancer-associated marker." (PMID 35155211, 2021). "Here, we show that the silencing of KDM4B, but not KDM4A/KDM4C, with specific shRNAs significantly reduced IL-8 production in gastric cancer cells." (PMID 30683841, 2019).
ovarian carcinoma (10 papers, 2017 to 2023). A malignant neoplasm originating from the surface ovarian epithelium. "KDM4B regulates genes associated with seeding of ovarian cancer cells to the peritoneal and omental tissues during metastasis (PDGFB, LOX, LOXL2, and LCN2)." (PMID 30759871, 2019). "In order to better understand the contribution of KDM4B to ovarian cancer progression, pathways regulated by KDM4B in normoxia and hypoxia were analyzed by QPCR." (PMID 34766154, 2021). "We have previously shown that KDM4B regulates peritoneal seeding of ovarian cancer (OVCAR) by demethylating the promoters of PDGFB, LOX, LOXL2, and LCN2 genes." (PMID 34766154, 2021). "KDM4B overexpression has been reported in many cancers, including colon, breast, prostate, and ovarian cancers." (PMID 34766154, 2021). "As a hypoxia-inducible regulator of peritoneal seeding, KDM4B represents a novel mechanism used by EOC cells to promote progression of ovarian cancer." (PMID 27869162, 2017). "KDM4B is a major factor affecting the prognosis of ovarian cancer." (PMID 35186950, 2021). "Additionally, high KDM4B expression was linked to poor OS prognosis for SARC, THCA, ovarian cancer, and poor RFS prognosis for SARC (p < 0.05)." (PMID 34766154, 2021). "Using immunohistochemical analysis of patient samples and in vitro and in vivo functional analyses of ovarian cancer cell lines, we have determined that KDM4B is abundantly expressed in EOC tumors, and contributes to multiple pathways required for peritoneal seeding." (PMID 27869162, 2017). "Combined, these results indicate that KDM4B may influence ovarian cancer progression by promoting formation of ascites spheroids in the peritoneal cavity and subsequent invasion of these clusters to peritoneal tissues." (PMID 27869162, 2017). "Expression of KDM4B was measured in ovarian cancer tissue microarrays (TMAs)." (PMID 27869162, 2017). "Moreover, the hypoxia-inducible KDM3A, which could demethylate H3K9me2/1 in hypoxic states, may promote the function of KDM4B in ovarian cancer." (PMID 30064416, 2018). "Specifically targeting KDM4B with shRNA increased KDM4D RNA and protein expression in ovarian cancer cells." (PMID 30759871, 2019). "In ovarian cancer, KDM4B is induced under hypoxia, and deletion of KDM4B increases H3K9me3 level at target gene promoters such as the LOXL2, LCN2, and PDGFB promoters, thereby inhibiting the invasion, migration and globulization of ovarian cancer cells." (PMID 35186950, 2021). "This does not mean that KDM4B is not important for mediating tumorigenic mechanisms in ovarian cancer, but it does mean that expression does not correlate with prognosis during conventional platinum-Taxol therapies." (PMID 30759871, 2019).
neuroblastoma (9 papers, 2017 to 2023). Neuroblastoma (NB) is the most common solid, extracranial childhood tumor. "Ciclopirox targeted KDM4B, inhibited Myc signaling, resulting in suppression of neuroblastoma cell viability and tumor growth associated with an induction of differentiation." (PMID 29342868, 2018). "While the elevated expression of KDM4B in N-MYC amplified neuroblastomas is associated with poor clinical outcome, inhibition of KDM4B suppresses MYC function." (PMID 28505071, 2017). "In neuroblastoma, the histone demethylase KDM4B was also found to bind to the acidic central region of the N-MYC protein, thereby coregulating the downstream MYC signaling pathway." (PMID 38093312, 2023). "Ciclopirox has also been found to be an effective KDM4B inhibitor that inhibits neuroblastoma cell proliferation, but has little effect on normal nerve cells." (PMID 35186950, 2021). "This is in contrast to reports in neuroblastoma, where stable silencing of KDM4B led to a reduction in cell proliferation and a concomitant induction of differentiation in these cells." (PMID 33917420, 2021). "Knockdown of KDM4B significantly inhibits the growth of neuroblastoma cells and neurite outgrowth, indicating that KDM4B is an important gene for maintaining the morphology of neuroblastoma cells." (PMID 35186950, 2021). "When KDM4B is knocked down, there is decreased proliferation, differentiation and tumor growth in neuroblastoma models." (PMID 30759871, 2019). "The expression of KDM4B was highly correlated with that of the MYCN oncogene in neuroblastoma, and it formed a complex with N-Myc protein, thereby facilitating its function by maintaining low levels of repressive H3K9me2/me3 marks at Myc-binding sites." (PMID 29342868, 2018). "The H3K9 demethylase, KDM4, has shown promise as a therapeutic target due to the discovery that KDM4B knockout in MYC-driven neuroblastoma cells resulted in downregulation of important MYC target genes, such as MIR17HG, CDC25A, SOX2, KITLG, VCAN, and SDC1." (PMID 28505071, 2017). "Loss of KDM4B function causes downregulation of N-MYC target genes, subsequently inhibits cellular proliferation, induces differentiation, and delays neuroblastoma tumor growth." (PMID 28505071, 2017). "KDM4B has also been shown to regulate the N-Myc pathway in neuroblastoma." (PMID 30759871, 2019). "KDM4B and N-Myc are highly expressed in neuroblastoma tumors and correlate with poor outcome." (PMID 30759871, 2019). "Recently, we showed that KDM4B is involved in neuroblastoma growth and tumor maintenance." (PMID 29342868, 2018). "Ciclopirox has been identified to be a powerful KDM4B inhibitor that diminishes the growth of neuroblastoma cells while having minimal impact on healthy nerve cells, suggesting that it could be employed to counter neuroblastoma." (PMID 37218871, 2023). "Moreover, KDM4B can interact with oncogenes to participate in downstream signaling pathways and play an intermediate regulatory role in prostate cancer, breast cancer, and neuroblastoma." (PMID 38093312, 2023). "In neuroblastoma, N-MYC physically interacts with the PHD/Tudor domain of KDM4B and recruits KDM4B to the promoter of N-MYC target genes, thus regulating the N-MYC signaling pathway." (PMID 35186950, 2021). "In NEPC with the absence of the AR, KDM4B could interact with N-Myc instead, where it has been shown to regulate and epigenetically activate this oncogene in neuroblastoma." (PMID 29757368, 2018).
colon carcinoma (7 papers, 2017 to 2025). "In contrast, high expression of KDM4B —an H3K9-specific demethylase—was linked to enhanced RFS prognosis in colon tumors (HR: 0.27, p = 0.028)." (PMID 33323965, 2021). "Additionally, we also evaluated KDM4B expression using colon cancer tissue microarrays, wherein we observed higher levels of KDM4B protein in colon tumour tissues compared to paired peri‐tumour specimens." (PMID 38390756, 2024).
leukemia (7 papers, 2017 to 2022). A malignant (clonal) hematologic disorder, involving hematopoietic stem cells and characterized by the presence of primitive or atypical myeloid or lymphoid cells in the bone marrow and the blood. "Consistently, murine Kdm4b deficiency reduced clonogenic activity of hematopoietic progenitor cells transduced with AE and AE9a, and impaired leukemia development in a mouse BMT model." (PMID 34938963, 2021). "At the same time, multiple studies have confirmed that multiple methylases strictly control the cell stemness, senescence and differentiation functions of MSCs, and the loss of KDM4B mimics a leukemia-like MSCs, suggesting that leukemia cells epigenetic change MSCs for its BMM remodeling." (PMID 35756991, 2022). "In this study, we report that KDM4B promotes the pathogenesis of AE‐induced leukemia in human cell lines and a mouse model, and highlight the leukemia‐promoting role of KDM4B." (PMID 34938963, 2021). "In this study, we demonstrated that KDM4B has a tumor‐promoting role in AE‐induced leukemia, using human cell line models and mouse genetic ablation." (PMID 34938963, 2021). "To address the role of KDM4B in leukemia development, we further generated and analyzed Kdm4b conditional knockout mice." (PMID 34938963, 2021). "To further explore the role of KDM4B in the development of leukemia, we established a polyinosinic‐polycytidylic acid (pIpC)‐inducible Kdm4b‐conditional knockout mouse model." (PMID 34938963, 2021). "As a result, Kdm4b deficiency attenuated clonogenic potential mediated by AML1‐ETO and delayed leukemia progression in vivo." (PMID 34938963, 2021). "A previous study revealed that combined activity of Kdm4a, Kdm4b, and Kdm4c is required for AML with a rearrangement of the mixed‐lineage leukemia gene (MLL‐AF9‐translocated AML) in vitro and in vivo, using Kdm4a−c triple knockout mice." (PMID 34938963, 2021). "Furthermore, only simultaneous knockout of the demethylases Kdm4a, Kdm4b, and Kdm4c perturbed progression of MLL-AF9 translocated leukemias in mice." (PMID 34944554, 2021). "We demonstrated that KDM4A and KDM4C, but not KDM4B, regulated leukemia progression." (PMID 35836814, 2022). "However, the carcinogenic mechanism of KDM4B in many tumors has not been deeply discussed and needs to be further studied, such as myeloma, lung cancer, leukemia, and classical Hodgkin lymphoma." (PMID 35186950, 2021). "The mechanism of KDM4B in leukemia is not well defined, and KDM4B expression is downregulated in chronic lymphoid leukemia (CLL), but KDM4B is known as an oncogene in acute lymphoid leukemia and its expression can be reduced using the spermidine analog Analogue-N 4-erucoyl Spermidine." (PMID 35186950, 2021).
lung carcinoma (7 papers, 2016 to 2024). "KDM4B has previously been shown to regulate CDK6 in bladder and lung cancer cells." (PMID 33917420, 2021). "Although the significance of KDM4B in lung cancer remains to be elucidated, a large proportion of KDM4B-positive patients have significantly poorer prognosis than do KDM4B-negative patients, and KDM4B may serve as a new prognostic factor after lung cancer resection." (PMID 35186950, 2021).
osteoporosis (7 papers, 2016 to 2025). A condition of reduced bone mass, with decreased cortical thickness and a decrease in the number and size of the trabeculae of cancellous bone (but normal chemical composition), resulting in increased fracture incidence. "For instance, the loss of epigenetic factor KDM4B in BMSCs exacerbates skeletal ageing and osteoporosis by reducing bone formation and increasing marrow adiposity through elevated H3K9me3." (PMID 39789420, 2025). "KDM4B deficiency in MSCs exacerbates skeletal aging and osteoporosis by increasing H3K9me3 to reduce bone formation and increase marrow adiposity." (PMID 36950693, 2023). "Loss of KDM4B increases global H3K9me3, thereby reducing bone formation and increasing marrow fat to exacerbate skeletal aging and osteoporosis." (PMID 35186950, 2021). "For example, KDM4B deletion gene in mice has been reported to cause osteoporosis and severe obesity." (PMID 35186950, 2021). "Loss of KDM4B may lead to adverse conditions such as hyperlipidemia and osteoporosis." (PMID 35186950, 2021). "KDM4B deletion in MSCs exacerbated skeletal aging and osteoporosis, thus reducing the bone formation and increasing marrow adiposity by elevating H3K9me3." (PMID 36950693, 2023). "Taken together, our findings establish KDM4B as a critical regulator of osteoclastogenesis, providing a potential therapeutic target for osteoporosis." (PMID 34031372, 2021). "Therefore, large-scale use of KDM4B inhibitors may inhibit the activity of KDM4B in normal cells, which may lead to adverse consequences, such as gonadal hypoplasia, osteoporosis and even obesity." (PMID 35186950, 2021).
osteosarcoma (6 papers, 2019 to 2024). A usually aggressive malignant bone-forming mesenchymal neoplasm, predominantly affecting adolescents and young adults. "Combined, these findings suggest that KDM4B is a novel risk factor or biomarker in osteosarcoma." (PMID 30759871, 2019). "Overexpression of KDM4C was found in non-small cell lung carcinoma and osteosarcoma, where upregulation of fibroblast growth factor 2, promoted by KDM4B/C modulates cell migration, invasion, and proliferation in osteosarcoma metastasis." (PMID 34778065, 2021). "KDM4B is upregulated in osteosarcoma compared with normal tissues and can promote fibroblast growth factor 2 (FGF2) upregulation, which promotes the proliferation, migration, and invasion of osteosarcoma cells." (PMID 35186950, 2021). "KDM4B has been connected to osteosarcoma tumorigenesis, a cancer type that effects young adults and is plagued with recurrence." (PMID 30759871, 2019). "Hsp90 has also been shown to stabilize KDM4B in osteosarcoma cell models, identifying Hsp90 inhibitors as a possible target for KDM4B driving tumor types." (PMID 30759871, 2019). "KDM4B also participates in regulating the DNA damage response in osteosarcoma models." (PMID 30759871, 2019). "SiRNA depletion of KDM4B was reported to abrogate DSB repair and sensitize osteosarcoma cells to IR." (PMID 39434131, 2024). "In osteosarcoma U2OS cells, the demethylase activity of KDM4B is critical for DSB repair." (PMID 39434131, 2024).
breast tumors (5 papers, 2011 to 2019). "KDM4A and KDM4B are considered promising therapeutic targets for prostate and breast tumor growth based on their functions as coactivators of androgen receptor and estrogen receptor, respectively." (PMID 30683841, 2019). "In particular, the alpha-glutarate-dependent dioxygenase KDM4B (aka, JMJD2B) has been shown to be important in G2/M progression and ER+ breast tumor growth in several models that include MCF750–53." (PMID 31171849, 2019).
Hepatic steatosis (5 papers, 2018 to 2023). Steatosis is a term used to denote lipid accumulation within hepatocytes. "Histone H3K9 demethylase, KDM4B, was recently reported to also contribute to hepatic steatosis through its control of the lipogenic transcription factor, ligand-activated liver X receptor α (LXRα)." (PMID 36650321, 2023). "A later study demonstrated that KDM4B plays a pivotal role in liver X receptor alpha (LXRα)-mediated lipogenesis, which provided another mechanism for KDM4B in hepatic steatosis." (PMID 37834101, 2023). "Specifically, the α-ketoglutarate-dependent Jumonji C (JmjC) domain-containing demethylase KDM4B (also known as JMJD2B) has been reported to promote hepatic steatosis by regulating the adipogenic transcription factor, PPARγ2, and lipogenic transcription factor, LXRα." (PMID 36650321, 2023). "In agreement, overexpression of KDM4B in the liver of mice stimulated LXR-dependent lipogenesis and induced hepatic steatosis." (PMID 36650321, 2023). "In addition, KDM4B/JMJD2B could upregulate PPARγ2 and its target genes related to lipid droplet formation and fatty acid uptake by removing H3K9 methylation to promote hepatic steatosis." (PMID 37834101, 2023). "Similarly, the H3K9 di- and tri-demethylase JMJD2B (KDM4B), involved in establishing the H3K9me activation mark, is upregulated in livers of diet-induced obese mice, resulting in increased hepatic PPARγ2 expression and induction of hepatic steatosis." (PMID 33193730, 2020).
hepatocellular carcinoma (5 papers, 2017 to 2022). A malignant tumor that arises from hepatocytes. "KDM4B shows increased expression correlating with tumor grade severity in Hepatocellular carcinoma (HCC)." (PMID 30759871, 2019). "Collectively, our results suggest that JIB-04-mediated targeting of histone demethylases, such as KDM4B, KDM4D, and KDM6B, inhibits the malignancy of hepatocellular carcinoma via growth inhibition and cell cycle arrest and, in addition, affects the maintenance and viability of liver CSCs." (PMID 35887001, 2022).
Obesity (5 papers, 2019 to 2025). Accumulation of substantial excess body fat. "More recently, two independent studies showed that the loss of KDM4B in adipocytes leads to increased obesity in mice on a high-fat diet." (PMID 31408999, 2019). "However, in mature adipocytes, KDM4B in turn acts to enhance metabolism, thereby counteracting obesity." (PMID 35186950, 2021). "Recent study shows that KDM4B protects against obesity and metabolic dysfunction." (PMID 31931846, 2020). "Together, these results suggest that, if we are able to modulate KDM4B activity, then we might be able to prevent obesity." (PMID 31408999, 2019). "If KDM4B also regulates adipose differentiation in humans, selectively increasing expression in adipose tissue could help treat obesity." (PMID 30759871, 2019).
bladder cancer (4 papers, 2016 to 2024). "KDM4B activity is also linked to liver, lung, and bladder cancer development." (PMID 30759871, 2019). "Knockdown of KDM4B in lung and bladder cancer models showed decreased proliferation and decreased colony formation, through decreased expression of CDK6." (PMID 30759871, 2019). "The roles of KDM4 family members, including KDM4A, KDM4B, KDM4C and KDM4D, on bladder cancer remains unclear." (PMID 39461328, 2024).
endometrial cancer (4 papers, 2015 to 2021). Primary or metastatic malignant neoplasm involving the endometrium (mucous membrane that lines the endometrial cavity). "One study exploring the role of androgen receptor (AC) in endometrial cancer suggested that KDM4B together with AR can activate the well-recognised oncogene, MYC, by removing H3K9me3 marks in endometrial cancer cells with high basal levels of AR." (PMID 33669182, 2021). "KDM4B has been shown to promote endometrial cancer progression by regulating androgen receptor, c-Myc, and p27kip1." (PMID 30759871, 2019). "However, in endometrial cancer, KDM4B modulates AR activity to promote endometrial cancer progression and was identified as a hub gene for cancer development by bioinformatics analysis." (PMID 35186950, 2021). "Expression of KDM4B and KDM4A is higher in endometrial cancer tissue compared to normal endometrium tissue." (PMID 33669182, 2021). "It is not clear if uterine KDM4B expression during miscarriage is related to its role in regulating the progression of endometrial cancer." (PMID 30759871, 2019).